IGLV1-50 (immunoglobulin lambda variable 1-50 (non-functional))
Description:
Probable non-functional open reading frame (ORF) of V region of the variable domain of immunoglobulin light chains. Non-functional ORF generally cannot participate in the synthesis of a productive immunoglobulin chain due to altered V- (D)-J or switch recombination and/or splicing site (at mRNA level) and/or conserved amino acid change (protein level). Immunoglobulins, also known as antibodies, are membrane-bound or secreted glycoproteins produced by B lymphocytes. In the recognition phase of humoral immunity, the membrane-bound immunoglobulins serve as receptors which, upon binding of a specific antigen, trigger the clonal expansion and differentiation of B lymphocytes into immunoglobulins-secreting plasma cells. Secreted immunoglobulins mediate the effector phase of humoral immunity, which results in the elimination of bound antigens. The antigen binding site is formed by the variable domain of one heavy chain, together with that of its associated light chain. Thus, each immunoglobulin has two antigen binding sites with remarkable affinity for a particular antigen. The variable domains are assembled by a process called V-(D)-J rearrangement and can then be subjected to somatic hypermutations which, after exposure to antigen and selection, allow affinity maturation for a particular antigen.
Synonyms: IGLV150; V1-18
Gene: Immunoglobulin variable (V) gene on chromosome 22 (22,327,300 to 22,327,814, forward strand). Ensembl gene ENSG00000211645.
Subcellular location: Secreted; Cell membrane
Gene Ontology:
Biological process: immune response
Cellular component: extracellular region; immunoglobulin complex; plasma membrane
Homologues: Paralogues in human: IGLV1-40 (86% identical), IGLV1-44 (76% identical), IGLV1-47 (75% identical), IGLV1-36 (73% identical), IGLV1-51 (73% identical), IGLV2-18 (72% identical), IGLV2-11 (69% identical), IGLV2-14 (69% identical), IGLV2-8 (69% identical), IGLV2-23 (66% identical), IGLV6-57 (64% identical), IGLV2-33 (62% identical), and 81 more.